RHOB (ras homolog family member B)
Diseases named in the same sentence as RHOB in open-access papers (continued):
Sharing a sentence is not in itself a finding about the gene and the disease.
breast carcinoma (continued). "The aim of this study was to examine the expression of ERM (ezrin, moesin) and Rho (RhoA, RhoB and Cdc42) proteins in breast cancer (BC) patients and to investigate the relationship between the sub-cellular localisation of these proteins and clinicopathological characteristics and patient survival." (PMID 23420497, 2013). "To confirm the clinical relevance of RhoB expression levels in breast cancer oncogenesis and outcome, we compared the expression levels of RhoB in breast carcinomas from a cohort of 113 patients treated or not by tamoxifen in an adjuvant setting in a randomized prospective study." (PMID 23339407, 2013). "An increase in RhoB mRNA is observed in some breast cancer cell lines." (PMID 15642170, 2005). "However, patients with breast cancer with overexpression of RhoB had better overall survival." (PMID 33162807, 2020). "Therefore, we hypothesize that atorvastatin may inhibit tumorigenesis by suppressing the PTEN/AKT pathway via upregulating the expression of RhoB in breast cancer." (PMID 31011573, 2019). "However, the mechanism of RhoB inhibition of breast cancer remains to be studied." (PMID 31011573, 2019). "Therefore, we speculated that ATO may suppress breast cancer cells by inhibiting the PTEN/AKT signaling pathway via upregulating RhoB." (PMID 31011573, 2019). "Thus, we conjecture that altered expression of RhoB induced by ATO might be decisive for breast cancer migration and progression." (PMID 31011573, 2019). "In addition, FAM53A may affect the migration and invasion of breast cancer cells by regulating the expression of RhoA, RhoB, RhoC, ROCK1, and MMP9." (PMID 31799197, 2019). "In this study, we investigated the expression of the ERM (ezrin, moesin) and Rho (RhoA, RhoB, Cdc42) protein families in a homogeneous group of patients with stage II invasive ductal breast cancer (BC)." (PMID 23420497, 2013). "In breast cancer cells, siRNA successfully reduced the expression of the Emi1 gene, and the expression level of the cell proliferation genes PDCD-4, FasL, PTEN and RhoB, along with invasive genes Maspin, TIMP3 and RECK, decreased significantly (P < 0.05)." (PMID 38041032, 2023). "RhoB is also involved in gastric cancer cells response to 5-FU, DOX and cisplatin treatments and in breast cancer cells MCF-7 cisplatin response." (PMID 36291810, 2022). "The modulation of RHOB and RHOG regulates the proliferation and differentiation of cancer cells, which influences the prognosis of breast cancer." (PMID 34991439, 2022). "Here, we report that degradation of an endosomal small GTPase, RhoB, by the ubiquitin ligase complex cullin-3 (CUL3)/KCTD10 is essential for both EGFR and HER2 phosphorylation in HER2-positive breast cancer cells." (PMID 34187934, 2021). "In HER2‐positive breast cancers, one of the most aggressive subtypes of breast cancer, KCTD10 induces RhoB degradation and activation of Rac1, which promotes progression of tumors, and resistance to therapy." (PMID 34001146, 2021). "The notion is supported our expression analysis using METABRIC database because the correlation between RhoB mRNA expression and prognosis of HER2-positive breast cancer patients were reversed dependent on expression level of EGFR mRNA." (PMID 34187934, 2021). "We previously reported that the constitutive degradation of an endosomal small GTPase RhoB by the CUL3/KCTD10 E3 complex functions in EGF-induced Rac1 activation specifically in HER2-positive breast cancer cell lines, among other breast cancer subtypes." (PMID 34187934, 2021). "To explore the role of RhoB in breast cancer, we knocked down RhoB in MCF-7 cells and overexpressed RhoB in MDA-MB-231 cells in accordance with RhoB protein levels in MCF-7 cells and MDA-MB-231 cells, followed by detection of cell biological effects." (PMID 31011573, 2019).
breast carcinoma (continued). "In summary, ATO inhibits the expression level of p-AKT by positively regulating the expression level of RhoB and increases the expression level of PTEN, thereby inhibiting the PI3K/AKT pathway and exerting its inhibitory effect on breast cancer." (PMID 31011573, 2019). "Subsequent experiments showed that RhoB significantly inhibited the proliferation, invasion and EMT of breast cancer cells, confirming that RhoB plays a role in tumor suppressor function in breast cancer cells." (PMID 31011573, 2019). "In a TCGA‐based analysis using the lung adenocarcinoma database, no RHOB mutation or deletion was found, which confirms previous observations in lung cancer and in our laboratory (unpublished data) or in other cancers such as head and neck carcinoma or breast cancer." (PMID 28003335, 2017). "The Ras homolog gene family member B (RHOB), a Rho GTPase, is up regulated in brain and breast cancer though down regulated in lung neoplasms." (PMID 19347046, 2009). "Nevertheless, RhoA and RhoB expression pattern has not been studied in the different subtypes of breast cancer and our study is the first to show a specific Rho expression pattern in basal-like/triple negative breast cancer." (PMID 33162807, 2020). "Furthermore, in breast cancer cells, we initially determined that ATO inhibits PTEN/AKT signaling pathway by upregulating RhoB." (PMID 31011573, 2019). "RhoB has been reported to exert positive and negative effects on cancer pathophysiology but an understanding of its role in breast cancer remains incomplete." (PMID 23339407, 2013). "RhoB overexpression has been correlated to disease progression, although this is a controversial issue, and overexpression of guanine exchange factors (GEF) for Rho GTPases have been correlated to prognosis in breast cancers." (PMID 23339407, 2013). "The second strand of evidence came from cellular results showing that the level of RhoB controls the expression of ERα in ERα-positive breast cancer cell in the presence or absence of E2." (PMID 23339407, 2013). "These GEFs activate RhoB, which is required for cell death after exposure to γ-IR in non-Ras transformed human breast cancer cells." (PMID 21373644, 2011). "Using the SurvExpress web tool, we found that RHOB expression had conflicted predictive value for cancer progression, whereas high VIM and ITGB2 expression were positively correlated with low metastasis-free/recurrence-free survival in lung adenocarcinoma and breast cancer cohorts." (PMID 35681731, 2022). "In breast cancer cells treated with atorvastatin, RT-qRCR was used to analyze the mRNA expression level of RhoB and PTEN, and Western blot was used to detect the protein expression level of RhoB or PTEN/AKT signaling pathway-related molecules-PTEN, AKT, and p-AKT." (PMID 31011573, 2019). "Furthermore, combined with clinical data, we found that RhoB expression levels were significantly higher in estrogen receptor-positive breast cancer tissues than in estrogen receptor-negative tissues." (PMID 31011573, 2019). "Thus, we conjecture that altered expression of RhoB induced by ATO may be decisive for the migration and progression of breast cancer." (PMID 31011573, 2019). "Besides the suggested specific involvement of RhoB in ER signaling, there have been no detailed investigations in breast cancer cells, including the assessment of any correlation with the expression of hormone receptors in tumors." (PMID 23339407, 2013). "Although previous reports indicated that FTI-treatment enhances the expression of RhoB in gastric cancer or breast cancer cells, in the present study, FTI-treatment did not enhance the expression of RhoB in BHP18-21v, FRO, or WRO cells." (PMID 25548921, 2014). "We therefore wanted to further explore the role of RhoB activation in a non-Ras transformed cellular system and utilized the breast cancer epithelial cell line, MCF-7, which contains endogenous RhoB." (PMID 21373644, 2011).
lung carcinoma (28 papers, 2007 to 2024). "In lung cancer, loss of RhoB accelerates lung cancer progression through activation of PI3K/Akt signaling pathway." (PMID 35538494, 2022). "An additional subset of patients with lung cancer demonstrates both the presence of cytoplasmic p27 and maintained RHOB expression, which was strongly associated with decreased patient survival." (PMID 31200451, 2019). "Loss of RhoB expression contributes to increased invasiveness of lung cancer through pathways such as PI3K/AKT and Rac1." (PMID 31200451, 2019). "From these results, we propose that RHOB levels can predict resistance to EGFR‐TKI in lung cancer tumors harboring an EGFR mutation." (PMID 28003335, 2017). "The present study offers a new strategy to increase the initial clinical response rate in EGFR‐mutated lung cancer patients by providing a molecular rationale for using EGFR‐TKI in combination with AKT inhibitor in patients harboring high RHOB tumor levels." (PMID 28003335, 2017). "In contrast to overexpression, loss or reduced expression of RhoB was observed in lung cancer and head and neck squamous cell carcinoma suggesting that loss of function of RhoB can contribute to oncogenic progression." (PMID 27104658, 2016). "Furthermore, in RhoB-deficient mice the number of Ras-induced tumours increased compared to wt-mice, and loss of RhoB led to increased metastatic dissemination of lung cancer cells, which was mediated by AKT." (PMID 37794133, 2023). "The downregulated RHOB has been observed in lung cancer, leading to the loss of its expression." (PMID 31217907, 2019). "Additionally, low RHOB expression has been shown to correlate with a positive response to treatment with EGFR-tyrosine kinase inhibitors (EGFR-TKI) in EGFR-mutated lung cancer patients, and reversely high RHOB expression correlates with a poor response." (PMID 31200451, 2019). "They speculated that the inhibition of RhoB by p27 might abrogate the selective pressure for RhoB loss in lung cancer." (PMID 30549261, 2019). "Overall, the present study offers a new strategy to increase the initial clinical response rate in EGFR‐mutated lung cancer patients by providing a molecular rationale for using EGFR‐TKI in combination with AKT inhibitor in patients harboring high RHOB tumor levels." (PMID 28003335, 2017). "We previously demonstrated RhoB loss of expression through lung cancer progression." (PMID 18047684, 2007). "Nevertheless, there was a poor prognosis in patients with low RhoB expression in lung cancer, gastric cancer, and pancreatic cancer patients." (PMID 39336777, 2024). "RhoB is often downregulated in malignancies like lung cancer and gastric cancer by suppressing the process of proliferation, migration, as well as invasion of tumor cells 28-30." (PMID 34093823, 2021). "RhoB overexpression in A549 human lung cancer cell lines suppress cell proliferation in vitro, and xenograft tumor growth in nude mice." (PMID 32392742, 2020). "RHOB is a known tumor suppressor in lung cancer, and its downregulation, frequently observed in aggressive tumors, is associated with decreased overall survival." (PMID 32733462, 2020). "The role of RHOB in the PAg-activation of Vγ9 T cells in lung cancer has to be depicted when Vγ9 T cells reactivity depends on the lung tumor cell lines status." (PMID 32733462, 2020). "This is supported not only by studies with genetically modified mice, but also through identification of a cohort of human lung cancer patients with cytoplasmic p27 and continued RhoB expression, where this signature correlates with decreased survival." (PMID 30549261, 2019). "It remains to be determined if the lung cancer promoting activities of p27CK− are solely due to RhoB inhibition." (PMID 30549261, 2019). "In lung cancer cell lines, the ectopic expression of RHOB can suppress anchorage-independent growth and cell proliferation." (PMID 31217907, 2019).
lung carcinoma (continued). "In vitro, studies have reported that RhoB, which is low-expressed in gastric cancer, lung cancer, ovarian cancer, and thyroid cancer cell lines, inhibits tumor cell proliferation, migration, and invasion." (PMID 31011573, 2019). "Our previous study showed that p38 pathway is involved in heat stress-induced RhoB expression in human lung carcinoma cell line A549." (PMID 28323887, 2017). "In lung cancer cells, we recently demonstrated that RHOB downregulation decreases PP2A activity, limiting AKT dephosphorylation and maintaining a high level of AKT activation." (PMID 28003335, 2017). "To further confirm that RHOB expression impacts on the response to EGFR‐TKI treatment, we downregulated or overexpressed RHOB by RNA interference and adenoviral transduction, respectively, in several EGFR‐mutated human lung cancer cell lines." (PMID 28003335, 2017). "The data provide a novel evidence that RhoB is important for cellular adaptation to hypoxia and hypoxia‐induced progression of lung cancer." (PMID 26915688, 2016). "In this study, we investigated the effects of hypoxia or/and Dex on the expression of RhoB in the lung of rats and human A549 lung carcinoma cells." (PMID 26915688, 2016). "In this study, we investigated the effects of hypoxia or/and GC on the expression and activition of RhoB in the lung of rats and human A549 lung carcinoma cells, and further studied its mechanism and significance." (PMID 26915688, 2016). "Taken together, the novel data revealed that hypoxia and Dex increased the expression and activation of RhoB, which is important for hypoxic adaptation and hypoxia‐accelerated progression of lung cancer cells." (PMID 26915688, 2016). "We have demonstrated previously that RHOB is downregulated by KRASV12 in lung cancer cell lines increasing invasiveness via AKT1." (PMID 26098773, 2015). "A correlation analysis between HDAC and RhoB expression in lung cancer is currently conducted in our laboratory." (PMID 18047684, 2007). "At the opposite, we demonstrated that RhoB silencing in lung cancer cells was reversed by histone deacetylating agents." (PMID 18047684, 2007). "Downregulation of RhoB has been shown in lung cancer cell lines and lung cancer tissues leading us to investigate the mechanisms leading to its loss of expression." (PMID 18047684, 2007). "As many genes are mutated in lung carcinomas (K-Ras, EGFR for example), mutational analysis of RhoB sequence has been performed by several teams in various tumors and were all negative." (PMID 18047684, 2007). "We reported that RhoB was expressed in normal and preinvasive tumors whereas its expression was weak and, most of the time, even lost in lung cancer invasive carcinoma." (PMID 18047684, 2007). "We first showed that histone deacetylase (HDAC) inhibitors induce a significant RhoB re-expression in lung cancer cell lines whereas only a slight effect was observed with methyl transferase inhibitors." (PMID 18047684, 2007). "We also showed that ectopic expression of RhoB in lung cancer cell line A549 suppressed cell proliferation, anchorage-independent growth, and xenograft tumor growth in nude mice." (PMID 18047684, 2007). "RhoB is down-regulated in most lung cancer cell lines and tumor tissues when compared with their normal counterparts." (PMID 18047684, 2007). "Regulation of RhoB expression in lung cancer appears to be complex and controlled by more than one mechanism." (PMID 18047684, 2007). "We showed in two independent immunohistochemical studies that RhoB protein was expressed in normal lung and decreased dramatically through lung cancer progression." (PMID 18047684, 2007). "We found that RhoB expression was lost lately in lung carcinoma and was correlated with tumor stage." (PMID 18047684, 2007). "Therefore, western blot and real-time PCR analyses were used to detect the expression of RhoA, RhoB, and RhoC in A549, H446 lung cancer cells transfected with plasmid Prox1 and interfering siRNA." (PMID 34183992, 2021).
lung carcinoma (continued). "Besides, recent study showed that the significant RHOB re-expression is induced by histone deacetylase (HDAC) inhibitors in lung cancer cell lines, indicating the expression of RHOB is mainly regulated by deacetylation and can support out results." (PMID 31217907, 2019). "While this study established a role of the RhoB/p27 axis in lung cancer, it will be important to elucidate if this mechanism also contributes to tumourigenesis in other organs and to uncover the crucial pathophysiological pathway affected by the RhoB/p27 axis." (PMID 30549261, 2019). "Together, these findings are exciting and open up the prospect that p27 and RhoB staining could be used as a biomarker in human lung cancer." (PMID 30549261, 2019). "Using lung cancer cells transfected with either an empty vector or a RhoB-overexpressing vector subcutaneously injected into nude mice, the authors confirmed this observation by showing a dramatic delay in tumor growth in the mice bearing tumors that overexpressed RhoB." (PMID 29385717, 2018). "Therefore, it appears that hypoxia‐induced RhoB is involved in hypoxia‐enhanced progression and metastasis of lung cancer cells." (PMID 26915688, 2016). "Thus, HDAC1 represses RhoB expression in lung cancer cells and treatment with the HDAC inhibitor, trapoxin A enhanced the transcription and expression of RhoB mRNAs." (PMID 25548921, 2014). "As many tumor suppressor genes are silenced by epigenetic modification in lung cancer, we hypothesized that RhoB expression might be repressed by either promoter methylation or histone deacetylation." (PMID 18047684, 2007). "Moreover, we observed that treatment of lung cancer cells with 5-Azacytidine induced a slight increase in RhoB expression." (PMID 18047684, 2007). "In vitro, it was shown that the RHOB/PP2A/AKT1/RAC1 pathway regulates mesenchymal migration and invasion in lung cancer through implication of a PP2A-B55 complex." (PMID 37170215, 2023). "However, it is unclear whether RhoB is involved the effect of hypoxia on lung cancer." (PMID 26915688, 2016). "While other proteins such as Rac, Ral and RhoB have previously been suggested to play a role in GGTI effects in other cell lines, our study suggests that the effects of P61A6 on H358 lung cancer cells are largely mediated by RhoA." (PMID 23607551, 2013). "RHOB which can have a dualistic role in cancer, was shown as conferring resistance to EGFR-tyrosine kinase inhibitors in lung cancer and frequently downregulated in aggressive lung cancer." (PMID 32733462, 2020). "In lung cancer cells devoid of RhoB, the application of HDAC inhibitors led to increased expression of RhoB, highlighting the notion that HDACs epigenetically control RhoB expression, and thus play a role in tumorigenesis." (PMID 31200451, 2019). "We first confirmed by Western Blot (not shown) and RT-PCR that RhoB expression was lost or decreased in most lung cancer cells and in lung tumors when compared with normal cell lines or normal tissues." (PMID 18047684, 2007). "We first analyzed RhoB expression by Western-blot and showed in A549 lung cancer cell line that treatment by 5-Azacytidine did not significantly increase RhoB expression." (PMID 18047684, 2007). "RhoB expression is also reduced or absent in lung cancer, compared to normal lung tissues." (PMID 32392742, 2020). "The mechanism by which RhoB expression decreases in lung carcinoma is not yet elucidated." (PMID 18047684, 2007). "As promoter methylation is the most common epigenetic process in lung cancer, we performed methylation specific PCR and sequence analysis after bisulfite treatment and demonstrated that RhoB was methylated neither in lung cancer cell lines nor in tumor tissues." (PMID 18047684, 2007).